IGHV4-28 (immunoglobulin heavy variable 4-28)
Description:
V region of the variable domain of immunoglobulin heavy chains that participates in the antigen recognition. Immunoglobulins, also known as antibodies, are membrane-bound or secreted glycoproteins produced by B lymphocytes. In the recognition phase of humoral immunity, the membrane-bound immunoglobulins serve as receptors which, upon binding of a specific antigen, trigger the clonal expansion and differentiation of B lymphocytes into immunoglobulins-secreting plasma cells. Secreted immunoglobulins mediate the effector phase of humoral immunity, which results in the elimination of bound antigens. The antigen binding site is formed by the variable domain of one heavy chain, together with that of its associated light chain. Thus, each immunoglobulin has two antigen binding sites with remarkable affinity for a particular antigen. The variable domains are assembled by a process called V-(D)-J rearrangement and can then be subjected to somatic hypermutations which, after exposure to antigen and selection, allow affinity maturation for a particular antigen.
Synonyms: IGHV428; VH
Gene: Immunoglobulin variable (V) gene on chromosome 14 (106,324,254 to 106,324,760, reverse strand). Ensembl gene ENSG00000211952.
Subcellular location: Secreted; Cell membrane
Gene Ontology:
Molecular function: antigen binding
Biological process: immunoglobulin mediated immune response
Cellular component: extracellular region; plasma membrane
Genetic constraint (gnomAD): Missense variants: 34 observed, 28.94 expected, observed/expected ratio (o/e) 1.17, 90% interval 0.89 to 1.56. Synonymous variants: 27 observed, 15.94 expected, observed/expected ratio (o/e) 1.69, 90% interval 1.22 to 1.96.
Homologues: Paralogues in human: IGHV4-39 (92% identical), IGHV4-4 (91% identical), IGHV4-59 (91% identical), IGHV4-61 (91% identical), IGHV4-31 (90% identical), IGHV4OR15-8 (89% identical), IGHV4-34 (84% identical), IGHV6-1 (64% identical), IGHV2-5 (56% identical), IGHV2-26 (55% identical), IGHV2-70 (54% identical), IGHV3-11 (54% identical), and 65 more.
Diseases named in the same sentence as IGHV4-28 in open-access papers:
IGHV4-28 is named in the same sentence as 1 disease in open-access papers, as found by Europe PMC text mining. Sharing a sentence is not in itself a finding about the gene and the disease. The quoted sentences say what the papers report.
multiple myeloma (1 paper, 2023). "Immunoglobulin gene IGKV1-33 is specifically expressed in P23 multiple myeloma patients (P = 5.3E-30, one-way analysis of variance), while IGHV4-28 is specifically expressed in P21 multiple myeloma patients (P = 1.8E-12, one-way analysis of variance)." (PMID 37155154, 2023).